MC4R (melanocortin 4 receptor)
Diseases named in the same sentence as MC4R in open-access papers (continued):
Sharing a sentence is not in itself a finding about the gene and the disease.
autism (2 papers, 2019). Persistent deficits in social interaction and communication and interaction as well as a markedly restricted repertoire of activity and interest as well as repetitive patterns of behavior. "The current study expands the application of pharmacologic MC4R stimulation by demonstrating that the MIA mouse model of autism is responsive to MT-II treatment, suggesting a promising approach for further clinical investigation regarding individuals with in utero exposure to infection." (PMID 30629642, 2019). "Also, another MC4R agonist called Ro27-3225 was shown to acutely reverse autism-like social deficits in Cntnap2 juvenile mice." (PMID 30629642, 2019). "Endogenous OXT release could also be stimulated pharmacologically to achieve more physiological-like conditions; for instance, MC4R agonists potentiate central OXT release and rescue social deficits in a mouse model of autism." (PMID 31998152, 2019).
brain injuries (2 papers, 2018 to 2020). "A majority of research on the benefits of melanocortins following neuroinflammatory insult and acquired brain injuries investigates MC4R-signaling via synthetic variants of α-MSH." (PMID 32670020, 2020). "A previous study demonstrated that the mRNA level of MC4R was increased in the contralateral striatum after hypoxia-ischemic brain injury in rats." (PMID 29642894, 2018).
Central hypothyroidism (2 papers, 2021 to 2022). A type of hypothyroidism due to an insufficient stimulation of an otherwise normal thyroid gland. "Instead, in POMC deficiency, central hypothyroidism seems to be a common occurrence, and the absence of MC4R stimulation could very well be the culprit here." (PMID 34177811, 2021). "It would be interesting to observe whether the stimulation of MC4R with an agonist such as setmelanotide would improve central hypothyroidism to any extent, but unfortunately, there were no reports of such results in the literature to date." (PMID 34177811, 2021). "The presence of central hypothyroidism in these cases can thus be considered an additional strong argument for the concept that there is indeed no or impaired cleavage of ACTH to α-MSH and d-α-MSH, and that they indeed do not activate the MC4R." (PMID 35737586, 2022).
Cognitive impairment (2 papers, 2023). Abnormal cognition is characterized by deficits in thinking, reasoning, or remembering. "Here, we also document the high incidence of delay in learning ability, possibly due to intellectual impairment, and aggressive behavior in children with LEP or LEPR deficiency that appear to be milder or absent in children with MC4R deficiency." (PMID 37659411, 2023).
colorectal tumor (2 papers, 2009 to 2025). "Overexpression of MC4R, as demonstrated by real-time PCR, immunofluorescence, and Western blot analysis, highlights the significant presence of this receptor in human ATC and colorectal tumor cells." (PMID 40004697, 2025).
Hirsutism (2 papers, 2019 to 2022). Abnormally increased hair growth referring to a male pattern of body hair (androgenic hair). "Moreover, the association of MC4R variants rs12970134 and rs17782313 with PCOS variables acne, loss of hair, hirsutism, PCOM, OA, BMI, HA, AMH, LH, FSH and LH/FSH ratio was studied using binary logistic regression." (PMID 31429705, 2019). "There is no direct association between the MC4R SNPs and PCOS, in addition to the other clinical variables such as acne, hirsutism, loss of hair, HA, PCOM and OA by using the chi-squared test." (PMID 31429705, 2019).
Hypoglycemia (2 papers, 2019 to 2025). A decreased concentration of glucose in the blood. "Separate cohorts of the PVH-specific MC4R-deficient mice (Mc4rloxP/loxP + AAV-Cre) were subjected to insulin-induced hypoglycemia or 2-DG-induced glucopenia using the same protocol as described for ArcPomc−/− mice." (PMID 30503832, 2019). "Moreover, the MC4R-deficient mice exhibited less than a twofold increase compared to a threefold increase in plasma epinephrine levels in the controls in response to hypoglycemia." (PMID 30503832, 2019). "To test the hypothesis, we induced hypoglycemia or glucopenia in separate cohorts of mice deficient in either POMC or MC4R in the arcuate nucleus (ARC) or the paraventricular nucleus of the hypothalamus (PVH), respectively, and measured their circulating counterregulatory hormones." (PMID 30503832, 2019). "We report that POMC in the ARC and MC4R in the PVH are indispensable to counteract hypoglycemia or glucopenia." (PMID 30503832, 2019). "Stimulation of epinephrine and glucagon release in response to hypoglycemia or glucopenia was diminished in both POMC- and MC4R-deficient mice, relative to their littermate controls." (PMID 30503832, 2019). "In conclusion, hypothalamic Pomc as well as Mc4r, both of which are reduced in type 1 diabetic mice, are required for normal counterregulatory responses to hypoglycemia." (PMID 30503832, 2019). "Overall, these findings demonstrate that MC4R in the PVH is essential for hypoglycemia counterregulation." (PMID 30503832, 2019). "Nevertheless, the POMC-Melanocortin 4 Receptor (MC4R) circuit is essential for the body’s ability to counteract hypoglycemia, as demonstrated by studies showing that POMC or MC4R deficiency impairs glucagon secretion and hepatic glucose production in diabetic mice." (PMID 41409607, 2025). "In addition to measuring the Pomc and Mc4r expression, we evaluated hypoglycemia counterregulatory response in the STZ diabetic mice." (PMID 30503832, 2019). "•Hypothalamic POMC as well as MC4R is necessary to counteract hypoglycemia." (PMID 30503832, 2019). "Yet, the necessity of hypothalamic POMC or MC4R in hypoglycemia counterregulation is unknown." (PMID 30503832, 2019). "The expression of c-fos was significantly higher in POMC and MC4R neurons in mice after insulin or 2-DG treatment compared to those injected with PBS, indicating that the neurons were activated following hypoglycemia or glucopenia." (PMID 30503832, 2019). "We employed FISH using RNAScope reagents to determine if hypoglycemia or glucopenia activate POMC and MC4R neurons in ARC and PVH, respectively." (PMID 30503832, 2019). "Using FISH to detect cfos mRNA, we demonstrated that POMC and MC4R neurons in the ARC and PVH, respectively, were activated following hypoglycemia." (PMID 30503832, 2019).
Infertility (2 papers, 2009). "We here report for the first time a decrease in the number of CL in obese MC4R-/- mice, which progresses early in reproductive life and likely causes infertility." (PMID 19309531, 2009).
ischemia (2 papers, 2020 to 2022). A hypoperfusion of the BLOOD through an organ or tissue caused by a PATHOLOGIC CONSTRICTION or obstruction of its BLOOD VESSELS, or an absence of BLOOD CIRCULATION. "Following ischemia, an MC4R-specific agonist improved injury-induced deficits in spatial learning." (PMID 32670020, 2020). "In particular, NDP-α-MSH interaction with melanocortin receptor 4 (MC4R), the most abundant MCR in the CNS and the only one present in microglia and astrocytes, has been already shown as an effective treatment for ischemia and early and moderate AD in experimental mouse models." (PMID 36703981, 2022).
Monogenic obesity (2 papers, 2023 to 2025). "Monogenic obesity due to MC4R pathogenic variants is the most common cause of severe childhood obesity." (PMID 38003551, 2023).
myocardial ischemia (2 papers, 2018 to 2021). A disorder of cardiac function caused by insufficient blood flow to the muscle tissue of the heart. "Similarly, ICV infusion of the MC4R agonist MTII in rats following myocardial ischemia improved cardiac structure and function, and attenuated the fall in HR." (PMID 34512392, 2021).
non-alcoholic fatty liver disease (2 papers, 2019 to 2025). "MC4R, melanocortin 4 receptor; KO, knockout; NAFLD, nonalcoholic fatty liver disease." (PMID 41266634, 2025).
peripheral nerve injury (2 papers, 2010 to 2016). Injury to a peripheral nerve. "The expression of MC4R has been shown to increase in the spinal cord after peripheral nerve-injury." (PMID 20856883, 2010). "A recent study showed that inhibition of melanocortin 4 receptor in the PAG not only blunts mechanical allodynia and thermal hyperalgesia but also delays the development of pain facilitation induced by peripheral nerve injury." (PMID 27504103, 2016).
teratoma (2 papers, 2021 to 2023). A non-seminomatous germ cell tumor characterized by the presence of various tissues which correspond to the different germinal layers (endoderm, mesoderm, and ectoderm). "The results demonstrated that Mc4r is also one of the genes responsible for OT formation and suggested that missense mutations in Mc4r promote teratoma formation in both sexes." (PMID 37127675, 2023). "It was suggested that the effect of the missense mutation in MC4R on teratoma formation was promoted by abnormal germ cell formation by the mutation in DND1." (PMID 33568756, 2021).
testicular teratoma (2 papers, 2021 to 2023). "By this study it was suggested that Mc4r is involved in the development of experimental testicular teratoma in mice." (PMID 37127675, 2023).
anaplastic thyroid carcinoma (1 paper, 2025). "Our data show that MC4R is present and highly expressed in human colorectal adenocarcinoma (wt Caco-2 and BRAF-mutated HT-29) and in anaplastic thyroid carcinoma cells (BRAF-mutated 8305C)." (PMID 40004697, 2025). "Furthermore, our study highlights the potential of MC4R-targeted therapies to address the unmet needs in the treatment of colorectal and anaplastic thyroid cancers." (PMID 40004697, 2025). "Background/Objectives MC4R expression and its role in colorectal and anaplastic thyroid cancers, where resistance to therapy and lack of standard treatments remain significant challenges, are poorly understood." (PMID 40004697, 2025).
aneurysm (1 paper, 2023). Bulging or ballooning in an area of an artery secondary to arterial wall weakening. "Moreover, in subjects with thoracic aortic aneurysm and/or AAA, macrophages-like cells obtained from lesions in aneurysm by laser capture microdissection showed lower MC4R gene expression than those obtained from non-lesions in aorta." (PMID 37957201, 2023).
Arrhythmia (1 paper, 2017). Any cardiac rhythm other than the normal sinus rhythm. "ECG rhythm strips of male Mc4r−/− mice also revealed a bradycardic arrhythmia with dropped p waves at the 30 week time point." (PMID 28829041, 2017).
benign brain tumor (1 paper, 2022). "On the other hand, MC4R and ETS1 in benign brain tumor are primarily associated with melanocortin receptor binding and regulating angiogenesis." (PMID 35887658, 2022). "Four signals associated with LRP1B (rs7599907), FRMD3 (rs10121898), MC4R (rs8087522), and ETS1 (rs76404385) identified benign neoplasms of the brain." (PMID 35887658, 2022).
brain neoplasm (1 paper, 2022). A neoplasm (disease) that involves the brain. "Other SNP profiles revealed different molecules, including DDP6, NDUFB9, EDARADD, EST1, MC4R, LRP1B, and FRMD3, which perform different roles in brain neoplasms or malignancies." (PMID 35887658, 2022).
carbohydrate metabolism disorders (1 paper, 2022). "The aim of the present study was to explore the association of polymorphisms within MC4R, PPARG, and TCF7L2 with the risk of different carbohydrate metabolism disorders and changes in the body composition in overweight or obese patients with early carbohydrate metabolism disorders." (PMID 35292917, 2022).
cardiomyopathies (1 paper, 2017). "Additional research will need to be conducted to determine the mechanism by which Mc4r deletion causes cardiomyopathy." (PMID 28829041, 2017). "Based on these results, loss of Mc4r appears to cause cardiomyopathy through an indirect mechanism." (PMID 28829041, 2017). "An age dependent cardiomyopathy was observed in male Mc4r−/− animals, which included cardiac dilatation and reduced contractility." (PMID 28829041, 2017). "Together, these results demonstrate that Mc4r deletion leads to a progressive cardiomyopathy." (PMID 28829041, 2017). "In this report, we describe the development of cardiomyopathy in Mc4r−/− mice." (PMID 28829041, 2017).
chronic kidney disease (1 paper, 2017). Impairment of the renal function secondary to chronic kidney damage persisting for three or more months. "Moreover, reduced muscle wasting was observed after administration of AgRP, the antagonist of MC4-R, in the animal model of chronic kidney disease (CKD)." (PMID 28358856, 2017).
cognitive decline (1 paper, 2021). "Instead, the MC1R and the MC3R, which have higher expression levels in the hippocampus than the MC4R and showed statistically significant correlations with the performance of aged rats in spatial learning and memory, may be better drug targets for the aging-related cognitive decline." (PMID 34684847, 2021).
dyslipidaemia (1 paper, 2021). "Odds ratio analysis of FTO rs9939609, MC4R rs17782313, ACE I/D rs4646994 and MTHFR C677T rs1801133 polymorphisms with somatometric and dyslipidaemia variables among the Liangmai and Mizo tribes of Manipur." (PMID 34414818, 2021). "Genetic interaction results between FTO rs9939609, MC4R rs17782313, ACE I/D rs4646994 and MTHFR C677T rs1801133 for somatometric and dyslipidaemia variables using generalized multifactor dimensionality reduction (GMDR)." (PMID 34414818, 2021).
endotoxemia (1 paper, 2022). "The binding of α-MSH to its receptor MC4R/MC3R promotes energy expenditure and weight loss, which are the vital determinants of muscle wasting during endotoxemia." (PMID 35428321, 2022).
glioblastoma (1 paper, 2025). The most malignant astrocytic tumor (WHO grade IV). "The PI3K/Akt pathway, which is frequently activated in various cancers, including glioblastoma, where it plays a key role in tumor survival and resistance to treatment, could interact with ERK1/2 signaling to amplify the therapeutic effects of MC4R inhibition." (PMID 40004697, 2025).
glucose metabolic disorders (1 paper, 2016). "Although MC3R deficiency led to a reduction of food consumption and body weight, it did show some additive effects on top of MC4R deficiency in both lipid and glucose metabolic disorders, which suggests different signalling pathways exist for MC3R." (PMID 27713523, 2016).
heart failure (1 paper, 2017). Inability of the heart to pump blood at an adequate rate to meet tissue metabolic requirements. "Together this study identifies MC4R deletion as a novel and potentially clinically important cause of heart failure." (PMID 28829041, 2017). "Since most phenotypes characterized in Mc4r+/-mice have translated to Mc4r+/-patients, patients with heterozygous Mc4r mutations should also be followed as our studies suggest they may have an increased risk for the development of heart failure." (PMID 28829041, 2017). "GSEA revealed that Mc4r−/− gene changes in the myocardium resemble that seen following doxorubicin treatment — a known inducer of ROS and heart failure." (PMID 28829041, 2017). "Mc4r−/− myocardium was examined to determine if the tissue displayed signs of heart failure, such as interstitial fibrosis or lipid deposition." (PMID 28829041, 2017). "Collectively, these studies characterize a novel form of heart failure with clinical importance and raise the need for further examination of how Mc4r deletion affects myocardial function in humans." (PMID 28829041, 2017).
intellectual disabilities (1 paper, 2025). "However, patients with MC4R pathway diseases will often present with intellectual disabilities, which may necessitate a proxy‐ or caregiver‐reported assessment." (PMID 40528426, 2025).
lipid metabolism disorders (1 paper, 2018). "In the study of Polish postmenopausal women, the presence of the T allele of the MC4R rs17782313 polymorphism was associated with considerably lower incidence of lipid metabolism disorders." (PMID 30271660, 2018).
Macrocephaly (1 paper, 2026). Occipitofrontal (head) circumference greater than 97th centile compared to appropriate, age matched, sex-matched normal standards. "Additionally, recent findings have identified macrocephaly as a common feature among individuals with MC4R deficiency, further expanding the phenotypic spectrum associated with these variants." (PMID 41489710, 2026).
malnutrition (1 paper, 2014). Inadequate nutrition resulting from poor diet, malabsorption, or abnormal nutrient distribution. "Changes in the relative expression of MC4R and AgRP mRNAs during long term malnutrition of rat indicate a stimulatory role of MC4R and AgRP in regulating energy balance in ARC of rat hypothalamus." (PMID 25317405, 2014).
neurofibromatosis (1 paper, 2021). A hereditary neoplastic syndrome in which tumors grow in the nervous system. "In at least one study, signs and symptoms associated with neurofibromatosis have been reported in one case with MC4R deficiency." (PMID 32952152, 2021).
ovarian teratoma (1 paper, 2021). A non-seminomatous germ cell tumor arising from the ovary. "From this, it can be speculated that the ligand of MC4R in the development of ovarian teratomas in this double-gene-modified line is AGRP." (PMID 33568756, 2021). "The results demonstrated that MC4R is one of the genes responsible for ovarian teratoma formation." (PMID 33568756, 2021).
overnutrition (1 paper, 2023). An imbalanced nutritional status resulting from excessive intake of nutrients. "Relevant gene defects, such as melanocortin 4 receptor (MC4R), Src-homology-2 (SH2B1), and potassium channel tetramerization domain-containing 15 (KCTD15), were found to be associated with excessive eating behavior and overnutrition." (PMID 36902691, 2023).
pancreatitis (1 paper, 2025). Inflammation of the pancreas. "Melanocortin receptors, specifically MC4R, play a role in pancreatitis." (PMID 41002740, 2025).
rectal cancer (1 paper, 2025). A primary or metastatic malignant neoplasm that affects the rectum. "In conclusion, this study introduces MC4R as a novel target for anticancer therapy in colon-rectal cancer and ATC." (PMID 40004697, 2025).
renal failure (1 paper, 2017). "While the cachexia syndrome could be ameliorated by blocking MC4-R signalling using genetic or pharmacological methods in renal failure, cardiac disease and acute LPS injection." (PMID 28358856, 2017).
Sepsis (1 paper, 2016). Sepsis is defined as life-threatening organ dysfunction caused by a dysregulated host response to infection. "We have shown previously that the microvascular inflammation in early sepsis in leptin deficient ob/ob, leptin resistant db/db and melanocortin 4 receptor knock out mice associated obese phenotypes are similar." (PMID 27500833, 2016).
thrombophilia (1 paper, 2025). A condition characterized by an abnormally high level of thrombi. "Furthermore, the presence of thrombophilia in the maternal grandmother and cardiovascular disease in the maternal grandfather underscores the broader metabolic risk context in this family, although these comorbidities were not directly linked to the MC4R variant." (PMID 40428329, 2025).
thyroid cancer (1 paper, 2025). "It was observable that 8305C thyroid cancer cells were positive for MC4R protein whereas in the absence of the antibody, they were negatively stained." (PMID 40004697, 2025).
type 1 diabetes (1 paper, 2019). "To understand molecular mechanisms elucidating the impaired hypoglycemia, we determined the expression of Pomc and Mc4r in the ARC and PVH, respectively, in type 1 diabetes mouse models." (PMID 30503832, 2019). "Moreover, we have demonstrated reduced expression of Pomc and Mc4r in the ARC and PVH, respectively, in two different mouse models of type 1 diabetes." (PMID 30503832, 2019).